CDKN2A (cyclin dependent kinase inhibitor 2A)
Diseases named in the same sentence as CDKN2A in open-access papers (continued):
Sharing a sentence is not in itself a finding about the gene and the disease.
tumor (continued). "Though different mechanisms of CDKN2A deletion exist in various human cancers, the CDKN2A tumor-suppression functions can be attenuated through point mutation, promoter hypermethylation, or deletion, and this could be one reason why this locus bears a high frequency of homozygous deletion." (PMID 31448219, 2019). "Additionally, expression levels of the downstream markers ZEB-2 and RAB-14 were downregulated, while those of the tumor suppressors CDKN2A, P63, and SIRT-1 were upregulated in the non-tumor specimens of LC patients with underlying respiratory disease compared to non-COPD patients." (PMID 29371906, 2018). "Indeed, the status of the CDKN2A gene is highly variable, with no detectable loss, hemizygous losses and homozygous losses of CDKN2A within the same tumor." (PMID 29848954, 2018). "In our integrated genomic and clinical analysis of TCGA, CDKN2A copy number loss was associated with poor prognosis in HPV-negative head and neck cancer independently of other known prognostic factors including age, advanced tumor stage, and African American race." (PMID 29670856, 2018). "Finally, we attempted to assess whether VHL loss, CDKN2A loss and MYC activation are dysregulated at tumour initiation or tumour progression, by analysing their relative frequency by TNM stage in the TCGA KIRC data set." (PMID 28593993, 2017). "To evaluate the relationship between nonpromoter CDKN2A methylation, RNA expression and tumor progression, we assessed the risk of locoregional recurrence (LRR) for the combined cohort of (n = 69) LXSCC patients from MMC, Pittsburgh, Vanderbilt, and UNC (median follow‐up of 26 months)." (PMID 28102032, 2017). "Focusing on the PVT1 chromosome interval representing circPVT1, we did not observe any difference between tumor samples with either FAT1 or CDKN2A mutations and those with an intact FAT1 or CDKN2A gene, which were both up-regulated in comparison to non-tumoral samples." (PMID 29262850, 2017). "In the dysplastic cell line POE9n tert, the observed pattern of CNAs is indicative of p16 (CDKN2A) inactivation and telomerase (TERT) activation; results of the assay are therefore consistent with an oncogenic pathway implicated in cellular immortalization and tumor progression." (PMID 28928368, 2017). "Therefore, the acceleration of MPNSTs upon somatic inactivation of cdkn2a/b in tp53e7/e7 mutant background may possibly be due to a reduction in apoptosis of affected tumor cells of origin." (PMID 28903419, 2017). "Typical alterations seen in IDHwt (primary) GBM such as EGFR amplification, chromosome 10 loss and homozygous deletion of CDKN2A were not present, although the observed gain of chromosome 7 and heterozygous deletion of 9p provide further evidence of the tumor’s astrocytic lineage." (PMID 26757882, 2016).
tumor (continued). "In addition, another lncRNA located within CDKN2B-AS intron, RP11-149I2.4, also showed more prominent expression in HPV16+ tumours and might be a novel regulatory lncRNA for HPV-associated CDKN2A over-expression." (PMID 29263803, 2016). "Furthermore, dGenhancer calculator, which allowed us to determine targets within TRβ1 5’UTRs, was also successfully used to design dGs enhancing translation of another CDKN2A tumor suppressor transcript, thus confirming the universality and potential of dGs to over-express selected proteins." (PMID 27171412, 2016). "Both techniques agreed on 30 tumours showing no LOH or copy number loss at CDKN2A." (PMID 27682877, 2016). "Accordingly, repression of RAE1, a mitotic checkpoint regulator, as well as CDKN2A, a tumor suppressor that inhibits G1/S transition and establishes cell cycle arrest, could further support the hypothesis of enhanced proliferative potential of NEXBTL100 extract." (PMID 27827897, 2016). "The CDKN2A gene, which codes for both the p16 protein and its alternate reading frame (p14ARF) is frequently affected by epigenetic gene silencing and deletion in other head and neck cancers, and both have been established as known tumor suppressors in head and neck carcinogenesis." (PMID 25619363, 2015). "Although loss of Ptprd and Cdkn2a may be targeted in cancer, our data does not rule out the potential role of other tumor suppressors on chromosome 9p, including Cdkn2b." (PMID 25138050, 2014). "We next determined whether Ptprd and Cdkn2a deletion altered the resultant tumor spectrum." (PMID 25138050, 2014). "The cyclin-dependent kinase inhibitor-2A gene (p16INK4a), located within the CDKN2A locus, is a strong and specific inhibitor of the progression through the G1 phase of the cell cycle by preventing phosphorylation of Rb protein and is considered a major tumour suppressor gene." (PMID 23717338, 2013). "Interestingly, it has been shown that MTAP can be lost independently of CDKN2A, which suggests that loss of MTAP may indeed play a role in tumor biology." (PMID 23029397, 2012). "Due to the potential importance for the CDKN2A C500G polymorphism and IDH1 mutations in GBM, the current study investigated the C and G 500 allele frequencies in genomic DNA, and IDH1 mutations in tumor DNA from 107 individuals with telomerase, ALT, and NDTMM GBMs." (PMID 22046342, 2011). "Promoter hypomethylation in tumor tissues correlated with overexpression of LAMC2, CTHRC1, CXCL13, FST, SPP1, and PLAU, whereas CDKN2A showed hypermethylation." (PMID 41776121, 2026). "Consistent with the transcriptomic findings, immunohistochemistry confirmed higher expression of NOX4, CXCL1, CDKN2A, and SIX1 in CRC tissues than in paired adjacent non-tumor tissues." (PMID 42317343, 2026). "While current CDKN2A-targeted cancer therapeutic strategies are still under exploration, a sequential approach that induces senescence followed by the elimination of senescent cells, or optimized combinations of therapeutic strategies with senolytics and senostatics, may enhance anti-tumor efficacy." (PMID 41614944, 2026). "We also observed the enrichment of CDKN2A (p16), SERPINB3, KRT5, and TP63, which are well‐established biomarkers for HPV‐positive neoplasia and are typically expressed in tumour areas." (PMID 41362277, 2026). "Recent translational work has highlighted the relevance of the tumor microenvironment and recurrent genomic alterations such as BAP1, NF2, and CDKN2A in shaping immune activity and potentially modulating response to immune checkpoint inhibitors." (PMID 41744857, 2026).
tumor (continued). "Survival was significantly worse when the tumor presented with both WHO grade 4 morphology and CDKN2A/B deletion." (PMID 40392514, 2025). "High-expressed CDKN2A is related to a poor prognosis in CRC through affecting the migration and invasion of the tumor cells." (PMID 39950044, 2025). "While a detailed breakdown of CDKN2A/B copy number status in INDIGO is pending, this study carefully deselected patients with more aggressive tumours by requiring a minimum 12-month observation period following their last surgery." (PMID 40136387, 2025). "Particular focus is placed on aberrant DNA methylation (e.g., hypermethylation of CDKN2A, RASSF1A) and altered histone modifications (e.g., EZH2‐mediated silencing) as indicators of tumor heterogeneity and evolution." (PMID 40959208, 2025). "CDKN2A (p16/Ink4a) and CDKN2B (p15/Ink4b) inhibit cyclin-dependent kinases and are important tumor suppressors." (PMID 39319854, 2025). "For the first time, cyclin‐dependent kinase inhibitor 2A (commonly abbreviated as p16) status and extracapsular spread (ECS) began to play an important role in the new tumor classification for OPSCC." (PMID 39906575, 2025). "Molecular analysis of tumor tissue identified CDK4 amplification and CDKN2A/B deletion in two patients with OS of >37 and 20 months, respectively." (PMID 41050069, 2025). "Further, genetic alterations of Cdkn2a have been shown to indicate HCC tumors with poor prognosis, suggesting a role of the p16 pathway in tumor aggressiveness." (PMID 40386382, 2025). "The positive expression rate of CDKN2A in LUAD was 84.04% (79/94), significantly exceeding the 47.67% (41/86) observed in adjacent non-tumor tissues." (PMID 41341386, 2025). "Recent studies have elucidated the involvement of tumor suppressor genes, such as PTEN (Phosphatase and Tensin Homolog) and CDKN2A (Cyclin-Dependent Kinase Inhibitor 2A), in the development and progression of different kinds of tumors." (PMID 41465387, 2025). "NGS analysis of the tumor biopsies confirmed the presence of CRISPR-induced edits in PTEN and CDKN2A in Oncopigs 2 and 3, indicating successful development of genetically tailored HCC in Oncopigs." (PMID 39780710, 2025).
tumor (continued). "CDKN2A and CDC20 expressions correlated significantly with stage and grade, while TGFB1, CDKN2A, and CDC20 were highly expressed in proliferative tumor cells." (PMID 40256740, 2025). "The indication is that CDKN2A and NINJ1 potentially impact tumor prognosis by regulating the infiltration of immune cells." (PMID 39980566, 2025). "We examined the expression levels of CDKN2A, NXPE4, and PLCB4 in normal and tumor tissues using data from the TCGA database." (PMID 39895793, 2025). "Results showed increased levels of CDKN2A and PLCB4 in tumor tissues, whereas NXPE4 expression was higher in normal tissues." (PMID 39895793, 2025). "The co-expression of CDKN2A and the immune checkpoint gene CD274 was enhanced with elevated tumor purity." (PMID 41341386, 2025). "Combining SOX2 overexpression with common tumor suppressors PTEN and CDKN2A leads to LUSC-like tumors in basal, alveolar type 2, and club cells." (PMID 40327401, 2025). "We observed upregulation of CDKN2A and WNT7B in tumor tissues, potentially driven by increased proportions of basal epithelial cells, ciliated epithelial cells, and stem-like adenocarcinoma cells." (PMID 41184502, 2025). "Tumor-related genes TRPM4, MYBL2, and CDKN2A were significantly upregulated and correlated with specific bacterial taxa." (PMID 40313460, 2025). "Methylation patterns of genes like CDKN2A and MLH1 also serve as prognostic indicators, correlating with tumor stage, grade, and patient outcomes." (PMID 40452892, 2025). "The 9p21.3 region encompasses three notable tumor suppressor genes, namely CDKN2A, CDKN2B, and MTAP, as well as a long noncoding RNA called ANRIL (antisense noncoding RNA at the ink4 locus non-coding gene)." (PMID 39443269, 2024). "In CRC primary tumours, the hypermethylation of bone morphogenetic protein 2 (BMP2), cyclin-dependent kinase inhibitor 2A (CDKN2A), and family with sequence similarity 134 member B (FAM134B) was associated with lymph node metastases." (PMID 38255946, 2024). "Read coverage at the CDKN2A and CDKN2B loci showed that tumor samples had relatively lower coverage, as compared to the normal samples, supporting shallow deletions." (PMID 39122888, 2024). "The cyclin dependent kinase inhibitor 2A (CDKN2A, also known as p16 or p19), a tumor suppressor, is essential for regulating the G1 to S phase transition in the cell cycle, controlling cell growth." (PMID 38844964, 2024). "Several tumour suppressor genes such as MTAP, CDKN2A and B, mapped to the locus 9p21, were shown to present with homozygous or heterozygous deletions accompanied by poor prognosis in multiple forms of cancer." (PMID 38164368, 2024). "Compared with those in adjacent tissues, the expression levels of CDKN2A, BIRC5, and SPP1 were significantly upregulated in tumor tissues (p < 0.05), while the expression of IGF1 was considerably downregulated (p < 0.001)." (PMID 39042294, 2024).
tumor (continued). "Further, genetic alterations or deletion of Cdkn2a are indicative of HCC tumors with poor prognosis, suggesting a role of the P21 pathway in tumor aggressiveness." (PMID 39605490, 2024). "In summary, we found significant CNA differences in CDKN2A, ERBB2, SMAD4, and CCNE1 between pNET and sbNET tumor samples after combined analyses of chromosomal microarrays, RNA sequencing, and fluorescence in situ hybridization data." (PMID 39062773, 2024). "Tumor cells sensitive to BR0063 exhibited several distinct phenotypes, including cell senescence, which was mediated by the up-regulation of CDKN2A/p16." (PMID 39500892, 2024). "CDKN2A, BIRC5, and SPP1 expression levels were significantly upregulated in tumor tissues (p < 0.001), while IGF1 expression was considerably downregulated (p < 0.001)." (PMID 39042294, 2024). "Although we analyzed CDKN2A homozygous deletion using an NGS panel, it may be detected by a variety of methods, including fluorescence in situ hybridization (FISH), whole-exome sequencing, global DNA methylation profiling, and detecting potential loss of p16 immunoreactivity in tumor cell nuclei." (PMID 39457569, 2024). "Both the sarco-sphere model as well as the corresponding tumor tissue harbored an in-frame EIF5A::USP6 fusion in chromosome 17, homozygous losses of CDKN2A/B and ATRK, a truncation in the NOTCH1 gene and a TCF3::SLC39A3 rearrangement." (PMID 37951844, 2024). "Usually, when analyzing the tumor genome by CMA, aberrations larger than 5 MB and additional microdeletions involving the CDKN2A/B, BTG1, EBF1, ETV6, ERG, IKZF1, PAX5, and RB1 genes are taken into account." (PMID 39408811, 2024). "The ARF tumor suppressor (p14ARF in humans and p19ARF in mice) was originally identified as an alternative transcript of the INK4b-ARF-INK4a (CDKN2A) locus located on human chromosome 9p21." (PMID 38870055, 2024). "Regarding the non-tumor tissue, the majority of samples (although slightly less than in tumors) also showed methylation of CDKN2A/p16INK4A (12/15) and RB1 (8/15)." (PMID 38716944, 2024). "Conversely, genes like CDKN2A, GLS, MTF1, and SLC31A1 exhibited marked upregulation in the tumor, suggesting distinct roles in the pathophysiology of the disease." (PMID 38898987, 2024). "Cyclin dependent kinase inhibitor 2A (CDKN2A) is a cell cyclin dependent kinase inhibitor (CDKI) composed of three exons, which is a tumor suppressor gene." (PMID 38206516, 2024).